POLD1 (DNA polymerase delta 1, catalytic subunit)
Description:
As the catalytic component of the trimeric (Pol-delta3 complex) and tetrameric DNA polymerase delta complexes (Pol-delta4 complex), plays a crucial role in high fidelity genome replication, including in lagging strand synthesis, and repair. Exhibits both DNA polymerase and 3'- to 5'-exonuclease activities. Requires the presence of accessory proteins POLD2, POLD3 and POLD4 for full activity. Depending upon the absence (Pol-delta3) or the presence of POLD4 (Pol-delta4), displays differences in catalytic activity. Most notably, expresses higher proofreading activity in the context of Pol-delta3 compared with that of Pol-delta4. Although both Pol-delta3 and Pol-delta4 process Okazaki fragments in vitro, Pol-delta3 may be better suited to fulfill this task, exhibiting near-absence of strand displacement activity compared to Pol-delta4 and stalling on encounter with the 5'-blocking oligonucleotides. Pol-delta3 idling process may avoid the formation of a gap, while maintaining a nick that can be readily ligated. Along with DNA polymerase kappa, DNA polymerase delta carries out approximately half of nucleotide excision repair (NER) synthesis following UV irradiation. Under conditions of DNA replication stress, in the presence of POLD3 and POLD4, may catalyze the repair of broken replication forks through break-induced replication (BIR). Involved in the translesion synthesis (TLS) of templates carrying O6-methylguanine, 8oxoG or abasic sites.
Synonyms: POLD; CDC2; CRCS10; IMD120; MDPL
Tractability: Small molecule: an approved drug acts on it; a structure with a bound ligand is known; it belongs to a druggable protein family. PROTAC: UniProt records ubiquitination sites on it; ubiquitination databases record sites on it; its protein half-life has been measured; a small molecule that binds it is known.
Target class: Enzyme; Transferase
Gene: Protein-coding gene on chromosome 19 (50,384,204 to 50,418,018, forward strand). Ensembl gene ENSG00000062822.
Subcellular location: Nucleus
Subcellular location (Human Protein Atlas): Nucleoplasm; Cytosol
Pathways (Reactome):
DNA Repair: Dual Incision in GG-NER; Dual incision in TC-NER; Gap-filling DNA repair synthesis and ligation in GG-NER; Gap-filling DNA repair synthesis and ligation in TC-NER; HDR through Homologous Recombination (HRR); PCNA-Dependent Long Patch Base Excision Repair; Recognition of DNA damage by PCNA-containing replication complex; Termination of translesion DNA synthesis
Cell Cycle: Polymerase switching on the C-strand of the telomere; Processive synthesis on the C-strand of the telomere; Removal of the Flap Intermediate from the C-strand; Telomere C-strand (Lagging Strand) Synthesis
DNA Replication: Polymerase switching; Processive synthesis on the lagging strand; Removal of the Flap Intermediate
Metabolism: Cytosolic iron-sulfur cluster assembly
Gene Ontology:
Molecular function: chromatin binding; damaged DNA binding; DNA binding; DNA polymerase activity; DNA-directed DNA polymerase activity; protein binding; 3'-5'-DNA exonuclease activity; 3'-5' exonuclease activity; enzyme binding; nucleic acid binding; nucleotide binding
Biological process: base-excision repair, gap-filling; DNA biosynthetic process; DNA replication; DNA synthesis involved in DNA repair; DNA-templated DNA replication; error-free translesion synthesis; fatty acid homeostasis; nucleotide-excision repair, DNA gap filling; DNA repair; DNA replication proofreading; response to UV
Cellular component: chromosome, telomeric region; delta DNA polymerase complex; membrane; nucleoplasm; nucleotide-excision repair complex; nucleus
Genetic constraint (gnomAD): Loss-of-function variants: 76 observed, 104.74 expected, observed/expected ratio (o/e) 0.73, 90% interval 0.6 to 0.88. The upper end of that interval is the gene's LOEUF score, 0.88, which puts it in group 3 of 6, group 1 being the genes least tolerant of losing a copy. Missense variants: 1,326 observed, 1,472.8 expected, observed/expected ratio (o/e) 0.9, 90% interval 0.86 to 0.94. Synonymous variants: 710 observed, 640.13 expected, observed/expected ratio (o/e) 1.11, 90% interval 1.04 to 1.18.
Gene-disease validity (ClinGen):
ClinGen rates the evidence that POLD1 causes each of these diseases.
mandibular hypoplasia-deafness-progeroid syndrome (autosomal dominant): Definitive.
non-severe combined immunodeficiency due to polymerase delta deficiency (autosomal recessive): Limited. Any non-severe combined immunodeficiency in which the cause of the disease is variation in the POLD1/POLD2 gene.
Cancer hallmarks: genome instability and mutations (suppresses); proliferative signalling (promotes); invasion and metastasis (promotes); cell replicative immortality; escaping immune response to cancer
Homologues: Orthologues: chimpanzee POLD1 (99% identical), pig POLD1 (95% identical), guinea pig POLD1 (91% identical), rat Pold1 (90% identical), mouse Pold1 (90% identical), macaque POLD1 (83% identical), zebrafish pold1 (69% identical), tropical clawed frog pold1 (67% identical), Drosophila melanogaster PolD1 (59% identical), Caenorhabditis elegans F10C2.4 (48% identical). Paralogues in human: REV3L (28% identical), POLA1 (21% identical), NEXMIF (9% identical).
Diseases named in the same sentence as POLD1 in open-access papers:
POLD1 is named in the same sentence as 163 diseases in open-access papers, as found by Europe PMC text mining. Sharing a sentence is not in itself a finding about the gene and the disease. The quoted sentences say what the papers report.
colorectal cancer (62 papers, 2014 to 2025). A primary or metastatic malignant neoplasm that affects the colon or rectum. "For instance, in colorectal cancer, POLD1 exonuclease domain mutations (e.g., p.S478N, p.L474P) correlate with elevated TMB and robust CD8+ T-cell infiltration, driving durable responses to anti-PD-1 therapy despite MSS status." (PMID 40661943, 2025). "The newly described POLD1:c.1481T>G p.(Ile494Ser) variant appears highly penetrant, as illustrated by family A: all carriers developed colorectal cancer between ages 32 and 66, with possible prior polyposis in some individuals." (PMID 41487566, 2025). "Both POLE and POLD1 mutations are incorporated into clinical guidelines for the management of endometrial and colorectal cancers." (PMID 41301688, 2025). "Mutations in the exonuclease domains of the POLE and POLD1 genes (present in ~1–2% and <1% of colorectal cancers, respectively) lead to a hypermutated phenotype characterized by defective DNA proofreading." (PMID 40805233, 2025). "We also sequenced and analyzed a colorectal cancer developed by a carrier of the pathogenic variant POLD1 D316H, which affects a catalytic site of the Polδ exonuclease." (PMID 38658779, 2024). "Germline mutations in the POLE and POLD1 genes, coding for DNA polymerases ε and δ, were described to be associated mainly with an increased risk of polyposis and colorectal cancer." (PMID 39684352, 2024). "Regarding SBS20, it is associated with defective DNA mismatch repair and microsatellite instability (MSI), commonly observed in stomach and colorectal cancers, potentially enriched with POLD1 mutations." (PMID 39350044, 2024). "It has been over a decade since the initial identification of exonuclease domain mutations in the genes encoding the catalytic subunits of replication DNA polymerases ε and δ (POLE and POLD1) in tumors from highly mutated endometrial and colorectal cancers." (PMID 37388540, 2023). "Mutations in POLD1 have been linked to several diseases, such as colorectal cancer, breast cancer, mandibular hypoplasia–deafness–progeroid syndrome (MDP), and Alzheimer’s disease." (PMID 37822923, 2023). "Previous studies have suggested that the alterations in POLD1 in humans are associated with multiple cancers, including hepatocellular carcinoma, colorectal cancer, endometrial cancer, and breast cancer." (PMID 37047824, 2023). "To date, colorectal cancer (CRC) seems to be the most extensively studied malignancy concerning POLD1 mutations." (PMID 36980791, 2023). "In the 37 brain tumor patients carrying rare POLE/POLD1 germline variants compiled here, gastrointestinal phenotypes were the most frequent additional features with colorectal adenomas in around 30%, and colorectal cancer in around 25% of cases." (PMID 37990341, 2023). "It is also reported that specific heterozygous germline mutations in the proofreading exonuclease-coding region and splicing sequences of POLE and POLD1 are associated with oligo-adenomatous polyposis, early-onset colorectal cancer and endometrial cancer." (PMID 37175782, 2023). "Colorectal cancers driven by somatic POLE mutations occur in 1–2% of colorectal cancers; POLD1 mutations are very uncommon." (PMID 36672501, 2023). "In the 10 families carrying POLE/POLD1 variants, other tumors were colorectal cancer (4/10, 40%), breast cancer (2/10, 20%), uterus cancer (1/10, 10%), prostate cancer (1/10, 10%), and small cell lung cancer (1/10, 10%)." (PMID 37990341, 2023). "In accordance with the tumor spectrum initially and most commonly described in PPAP patients, we observed colorectal cancer in four of 10 (40%) families with rare POLE/POLD1 germline variants." (PMID 37990341, 2023). "Pathogenic germline variants in the DNA polymerase genes POLE and POLD1 cause polymerase proofreading-associated polyposis, a dominantly inherited disorder with increased risk of colorectal carcinomas and other tumors." (PMID 37990341, 2023).
colorectal cancer (continued). "For example, we have shown that only a specific in-frame deletion that affects the polymerase domain of POLD1 causes a lipodystrophy syndrome, whereas mutations in the exonuclease domain have been shown to cause colorectal cancer." (PMID 35235652, 2022). "Due to the missense mutation in the proofreading domain of POLD1, there is a theoretical predisposition for colorectal cancer." (PMID 35356184, 2022). "Previous studies suggested that POLD1 proofreading domain mutations were identified as predisposing to a range of cancers, including colorectal cancer, endometrial cancer, skin squamous cell carcinoma, breast cancer, and brain tumor." (PMID 35189839, 2022). "Based on this concept, multiple studies demonstrated that colorectal cancer with deficient POLD1 activity possessed the increased sensitivity to ATR and CHK1 inhibitors in preclinical models." (PMID 35189839, 2022). "The polymerase proofreading-associated polyposis syndrome (PPAP) with missense mutations in the POLE- or POLD1-gene was recently described as cause of a new polyposis syndrome with development of colorectal cancers." (PMID 34118935, 2021). "Pathogenic POLD1 mutations have been observed in colorectal cancers and polymerase proofreading-associated polyposis syndrome." (PMID 35002543, 2021). "The main causes of TMB-H in colorectal cancer include POLE/POLD1 deficiencies and MSI-H resulting from MMR mutation or MLH1 promoter hypermethylation." (PMID 33194656, 2020). "One example of the significance of POLD1 polymerase domain alterations in colorectal cancer is a mutation leading to R689W change in pol III motif." (PMID 33255191, 2020). "Pathogenic variants affecting the exonuclease domains of POLE and POLD1 are associated with polyposis and colorectal cancer." (PMID 30827058, 2019). "The overall frequency of POLD1 mutations in lung cancer, colorectal cancer, and all cancers in COSMIC database were 1.3% (56/4232), 3.0% (56/1853), and 1.2% (572/48271), respectively." (PMID 31673068, 2019). "Germline mutations in POLE and POLD1 have been shown to cause predisposition to colorectal multiple polyposis and a wide range of neoplasms, early-onset colorectal cancer being the most prevalent." (PMID 28423643, 2017). "Mutations in the proofreading domains of POLE and POLD1 were also reported in two human colorectal cancer cell lines (DLD-1 and LoVo) and 1/76 colorectal cancer patients, all three samples exhibiting MMR deficiency." (PMID 24705290, 2014). "Moreover, most colorectal cancers with POLE/POLD1 mutations exhibit a microsatellite stable (MSS) phenotype." (PMID 40308511, 2025). "Similarly, the genes encoding for the proofreading polymerases POLE and POLD1 displayed significantly higher mutation rates in CDX2-suppressed colorectal cancers." (PMID 39452477, 2024). "Moreover, POLE/POLD1 variants carriers direct to associated phenotype characterized by attenuated or oligo-adenomatous colorectal polyposis, colorectal cancer, and brain tumors." (PMID 36685880, 2022). "Various POLD1 variants have been found in colorectal cancer, but their significance as therapeutic targets for ATR pathway inhibition remains unknown." (PMID 33144657, 2020). "Moreover, POLE/POLD1 mutation was identified in 0.65–12.3% of colorectal cancer patients and was reported to occur more frequently in EO CRC patients." (PMID 33194656, 2020). "Germline pathogenic variants in the exonuclease domain (ED) of polymerases POLE and POLD1 predispose to adenomatous polyps, colorectal cancer (CRC), endometrial tumors, and other malignancies, and exhibit increased mutation rate and highly specific associated mutational signatures." (PMID 32792570, 2020). "Additionally, POLE and POLD1 somatic mutations can give rise to a Lynch syndrome‐like phenotype and microsatellite instable colorectal cancer." (PMID 30827058, 2019). "For colorectal cancer, the estimated risk by age 70 is around 90% in POLE heterozygotes versus 50% in POLD1 carriers." (PMID 41487566, 2025).
colorectal cancer (continued). "For example, POLD1-mutant MSS colorectal cancers exhibit higher tumor-infiltrating lymphocyte density and cytotoxic T-cell markers compared to POLD1 wild-type MSS tumors." (PMID 40661943, 2025). "To better understand how such a weak mutation rate modifier can drive a highly penetrant cancer phenotype, we sequenced a tumor sample from the family with POLD1 L474P (colorectal cancer developed by individual IV.1)." (PMID 38658779, 2024). "In two recently published siblings with polyposis and a first colorectal cancer diagnosis as teenagers, a heterozygous PMS2 PV and a heterozygous POLD1 exonuclease domain variant were found." (PMID 39031223, 2024). "In the family, most POLD1 L474P carriers had been diagnosed with multiple colorectal polyps, colorectal cancer, and/or endometrial cancer." (PMID 38658779, 2024). "Some of these B-family DNA polymerase members, e.g. POLD1 and POLE, are already known to be mutated in some familial colorectal carcinomas and adenomas." (PMID 39128273, 2024). "It is estimated that genetic defects in POLD1 account for 0.2% of early-onset familial colorectal cancer." (PMID 37175782, 2023). "Pathogenic variants in POLE and POLD1 cause PPAP syndrome (polymerase proofreading-associated polyposis), where there is an increased risk of developing colorectal cancer." (PMID 36232851, 2022). "Current biomarkers for anti-PD1 in colorectal cancer, MSI/MSS, TMB, PDL1, and POLE/POLD1 mutation, share the same notion that anti-PD1 resistance is dominantly caused by one homogenous factor of an insufficient amount of CD8+ T-cell infiltration." (PMID 34594218, 2021). "Cancers of the colorectum and endometrium are the predominant types associated with germline and somatic POLE/POLD1 mutations." (PMID 34594041, 2021). "The analyzed colorectal cancer cases with pathogenic mutation in POLE, POLD1 and MSI were all identified to have signature a, which was characterized by structural deletion with size between 1 K–10 K." (PMID 32245405, 2020). "The frequency of variation in POLD1 in lung cancer, colorectal cancer, and all cancer patients was 2.5% (13/516), 3.2% (14/434), and 2.3% (32/1392), respectively." (PMID 31673068, 2019). "However, the DNA polymerase δ 1 catalytic subunit (POLD1) co-expressed with AC245041.1 was found to be associated with the prognosis of liver cancer, colorectal cancer, and endometrial cancer." (PMID 40019657, 2025). "Similarly, elevated POLD1 expression has been verified via independent researches in several cancers, including hepatocellular carcinoma, breast cancer, and colorectal cancer." (PMID 37047824, 2023). "NTRK‐driven colorectal cancer patients demonstrated increased TMB (median = 53 mut/MB, 95% CI: 36.8–68.0 mut/MB), high microsatellite instability, and an enrichment for POLE/POLD1 mutations when compared to molecularly unstratified colorectal cancer population." (PMID 35506567, 2022). "In addition to MSI/MSS status, other biomarkers such as TMB, PDL1, POLE/POLD1 mutation, or MSI-like gene signature are also used in colorectal cancer." (PMID 34594218, 2021). "This hypothesis should be tested in future studies through the individual introduction of single POLD1 variants (including the POLD1R506H variant), and consecutive characterization of their functional relevance in colorectal cancer cells." (PMID 33144657, 2020).